NOS1AP (nitric oxide synthase 1 adaptor protein)
Diseases named in the same sentence as NOS1AP in open-access papers (continued):
Sharing a sentence is not in itself a finding about the gene and the disease.
tumor (5 papers, 2016 to 2024). "If NOS1AP supports the tumor suppressor function of SCRIB, depletion of NOS1AP in MCF7 KANK1-KO cells should foil the effect of KANK1 on SCRIB-mediated TAZ stability regulation." (PMID 39613731, 2024). "Together, t﻿his supports the notion that both NOS1AP isoforms affect cellular proliferation and may function as a tumor suppressor." (PMID 28222762, 2017). "The KANK1-induced disruption of the SCRIB/NOS1AP complex curbs TAZ inhibition, resulting in increased mouse tumor cell growth in vivo, in tumoroids and in xenografted human cancer cells." (PMID 39613731, 2024). "In the present study, we find that KANK1 promotes tumor growth by changing the subcellular location from integrin adhesions to cell-cell junctions, where KANK1 competes with SCRIB for the binding to NOS1AP." (PMID 39613731, 2024). "Further studies will help determine if NOS1AP isoforms, Scribble and Hippo components will be useful biomarkers in OPSCC tumor biology." (PMID 28222762, 2017).
cancer (3 papers, 2016 to 2023). A tumor composed of atypical neoplastic, often pleomorphic cells that invade other tissues. "How NOS1AP functions to control Hippo signaling will be an important future focus in cancer biology." (PMID 28222762, 2017). "As such, more patients with HPV-positive OPSCC are being recruited to extend our findings and to develop a sense of how the Scribble-NOS1AP-Hippo signaling cascade may differ according to cancer grade." (PMID 28222762, 2017). "Interestingly, the VANGL/SCRIB/NOS1AP complex only assembles in cancer cells, while normal mammary epithelia show no co-localization of NOS1AP with either VANGL or SCRIB." (PMID 36675340, 2023). "The totality of these data supports the notion that a coordinated deregulation of SCRIB, VANGL2 and NOS1AP at the gene dosage or transcription level, possibly in conjunction with other PCP protein abnormalities, may affect cancer cell behavior in a sub-type-specific manner." (PMID 36675340, 2023).
cardiovascular diseases (3 papers, 2014 to 2023). "Despite this disparity of views, a consensus is emerging that nNOS:NOS1AP interaction is a potential drug target for neurological and cardiovascular disorders." (PMID 25221472, 2014). "The rapidly accumulating reports linking NOS1AP to psychiatric and cardiovascular diseases increase focus on the druggability of NOS1AP functions." (PMID 25221472, 2014).
heart diseases (2 papers, 2023 to 2024). "For evaluation of structural heart diseases due to cardiac specific Nos1ap over‐expression fibrosis staining of heart cross sections were conducted using mice with 3 months of Nos1ap over‐expression compared to controls." (PMID 36352324, 2023).
neurodegenerative disease (2 papers, 2017 to 2024). A disorder of the central nervous system characterized by gradual and progressive loss of neural tissue and neurologic function. "Nos1ap, nitric oxide synthase 1 adaptor protein, may play a role in excitotoxic neuronal damage in neurodegenerative disease." (PMID 38587883, 2024).
NOS1AP also shares sentences with these, for which no sentence is quoted: post-traumatic stress disorder (6 papers); Alzheimer disease (4); bipolar disorder (3); tauopathy (3); amyloidosis (2); Atrophy (2); autism spectrum disorder (2); Brain atrophy (2); coronary artery disease (2); mood disorder (2); neurological diseases (2); obsessive-compulsive disorder (2); Stroke (2); amyotrophic lateral sclerosis (1); atrial fibrillation (1); brain glioma (1); Brugada syndrome (1); cardiac arrhythmia (1); Cerebral arteriovenous malformation (1); cognitive deficits (1); death (1); Dependence (1); diabetic neuropathy (1); frontotemporal lobar degeneration (1); ganglionitis (1); glioblastoma (1); glioma (1); hippocampal atrophy (1); intracranial aneurysm (1); ischemia (1).
A further 11 diseases each share a sentence with NOS1AP in 1 paper.